KRT5 (keratin 5)
Diseases named in the same sentence as KRT5 in open-access papers (continued):
Sharing a sentence is not in itself a finding about the gene and the disease.
breast carcinoma (continued). "While proteins such as vimentin and Plastin 3 showed no notable changes, other EMT markers like Keratin 5 and E-Cadherin were affected, suggesting that although similar pathways may be involved, distinct proteins play central roles in breast cancer and NSCLC." (PMID 40301999, 2025). "Similarly, KRT5, KRT6, KRT14, and KRT17 are known to be expressed by both breast cancer and SKCM." (PMID 35267493, 2022). "Furthermore, some of the most well-known genes for basal-like breast cancer, such as keratin 5 and keratin 17, were not even significantly different between our TN and non-TN samples." (PMID 22140552, 2011). "The most widely used panel is based on the expression of cytokeratin 5/6 (CK5/6) and/or the epidermal growth factor receptor (EGFR) in tumors that are triple-negative; however, no uniform consensus exists as to what is the optimal immunnohistochemical panel to identify basal-like breast cancer." (PMID 20979652, 2010). "Notably, the genes LDHB, MMP7, KRT5, KRT14 and KRT15, which were significantly upregulated in the PIPET_Basal subpopulation, are recognized as specific biomarkers of the basal-like molecular subtype or genes typically highly expressed in basal-like breast cancer." (PMID 38819254, 2024). "Gene expression studies have previously identified only KRT5 mRNA and not KRT6 isoforms in normal breast and basal-like breast cancer in humans." (PMID 28147318, 2017). "Basal-like breast cancers are also aggressive, with overall poorer prognosis, negative for ESR/PR/Her2 and positive for HER1+ and cytokeratin 5/6+." (PMID 25100201, 2014). "We confirmed the origin of the foci by immunostaining for cytokeratin 5, which was determined to be present in the MMTV-Ron mammary tumors and not in hepatocytes (data not shown)." (PMID 22226043, 2012). "Later, Basal-like breast cancer (BLBC) was defined as estrogen receptor (ER) negative, human epidermal growth factor receptor 2 (Her-2) negative; epidermal growth factor receptor (EGFR, also known as Her-1) or/and Cytokeratin 5/6 (CK 5/6) positive." (PMID 31462314, 2019).
squamous cell carcinoma (113 papers, 2006 to 2026). A carcinoma arising from squamous epithelial cells. "Another type II cytokeratin, KRT5, has been previously associated with squamous cell carcinoma (SNP IDs rs11170164—chromosome 3:188370473 and rs607860)." (PMID 40650045, 2025). "Genes associated with squamous cell cancer, KRT5, cystatin A (CSTA) tumor protein p63 (TP63) and SOX2, were expressed at higher levels in ASC, but also expressed to some extent in the AC." (PMID 24324581, 2013). "To verify the histological origin of EP cell lines as lung adenocarcinoma, we evaluated the expression of adenocarcinoma markers Ttf1 and Napsa, as well as squamous cell carcinoma markers Krt5 and Np60 by qPCR." (PMID 41356800, 2026). "Cytokeratin 5/6, a high molecular weight cytokeratin, serves as a marker for squamous cell carcinoma." (PMID 40061900, 2025). "Among the KRT family members, KRT5 has been used as a single marker or in combination with KRT6 (KRT5/6) for antigen-specific immunohistochemical diagnosis of squamous cell carcinoma." (PMID 37671092, 2023). "Meanwhile, we observed less than 20% sporadic lung tumors resembling a feature of squamous cell carcinoma, such as the typical nests of neoplastic squamous cells with positive staining p63 and Krt5." (PMID 34381046, 2021). "One detectable difference was the expression of the basal stem and squamous cell carcinoma marker Krt5." (PMID 33738287, 2021). "According to our results, both Cytokeratin 5 and c-Myc were able to distinguish squamous cell carcinomas from adenocarcinomas, and their signal was particularly strong in LUSC and HNSC." (PMID 32601356, 2020). "p63, p40, and cytokeratin 5/6(CK5/6) are the most common panel of immunochemical markers for the diagnosis of squamous carcinoma." (PMID 32843061, 2020). "In the positive lymph node, round undifferentiated carcinoma cells were admixed with squamous carcinoma cells that were positive for cytokeratin 5/6 and 34βE12." (PMID 30649642, 2019). "Some immunohistochemistry studies have found the dual expression of both p63 and cytokeratin 5/6 with a specificity of 99% and a sensitivity of 98% for squamous cell carcinoma." (PMID 26185704, 2015). "Most cytopathology laboratories currently employ an IHC panel in these cases as an adjunct to aid tumor sub-classification, including TTF-1, Napsin A (positive in adenocarcinoma), cytokeratin 5/6 and P63 (positive in squamous cell carcinoma)." (PMID 22547449, 2012). "Cytokeratin 5 is highly expressed in mesothelium of basal layers in stratified epithelia, and is a marker for mesothelioma and squamous cell carcinoma." (PMID 22363815, 2012). "All specimens were analysed for expression of MAdL, TTF-1, SP-A, SP-B and, in case of squamous cell carcinoma, cytokeratin 5/6." (PMID 21811254, 2011). "Cytokeratin 5 is commonly used as an immunohistochemical marker for squamous cell carcinomas." (PMID 32601356, 2020). "However, according to a recent review article, mesothelin is positive in 27% of squamous cell carcinomas, and calretinin and cytokeratin 5/6 can be raised in both squamous cell carcinoma of the lung and adenocarcinoma of both the lung and other sites." (PMID 19099560, 2008). "A proposed five-gene diagnostic signature, including KRT5, MUC1, TREM1, C3, and TMPRSS2, as well as an eight-gene classifier for lung cancer subtypes, exhibited a high predictive accuracy of 0.936 during testing on 2556 adenocarcinoma samples and 1630 squamous cell carcinoma samples." (PMID 38612418, 2024). "Compared to the mouse squamous cell carcinoma cell line KLN-205, EP cells exhibited markedly higher expression of Ttf1 and Napsa, while the expression of Krt5 and Np60 was significantly lower." (PMID 41356800, 2026). "The aim of this study was to examine the combination of cytokeratin 5/6, p63, p40, and MUC5AC for distinguishing squamous cell carcinoma (SCC) from the adenocarcinoma in the cervix (AEC)." (PMID 32843061, 2020).
squamous cell carcinoma (continued). "In the following study, we examined the combination of cytokeratin 5/6, p63, p40 and MUC5AC for distinguishing squamous cell carcinoma (SCC) from adenocarcinoma of the cervix (AEC)." (PMID 32843061, 2020). "The high molecular weight keratins (KRT5, KRT6 and KRT14) that characterize basal MIBCs are also enriched in a lethal “squamous cell carcinoma” MIBC subtype identified by another independent research group." (PMID 30550540, 2018). "In three cases, the original diagnosis was squamous carcinoma due to cytokeratin 5 immunohistochemical expression, which we were not able to recognize with the limited use of immunohistochemistry and thus made a diagnosis of a NSCLC NOS." (PMID 39335769, 2024). "KRT5 and TP63 are known as the squamous cell carcinoma (SCC) of the lung-specific genes." (PMID 35584089, 2022). "Squamous cell carcinoma biomarkers such as TP63 (tumor protein p63), CK5/6 (cytokeratin 5/6), 34βE12 (high molecular weight cytokeratins) could also be identified in adenocarcinoma." (PMID 29137182, 2017). "However, a key difference emerged: KPGEMM tumors expressed the basal stem and squamous cell carcinoma marker Krt5, while KPCRISPR tumors did not." (PMID 40896696, 2025). "Notably, Krt5 was positive in KPGEMM tumors, while Sox2, a marker linked to squamous cell carcinoma, was absent in all samples." (PMID 40896696, 2025). "By validating the expression profiles of six specific genes (MIR205HG, KRT5, KRT6A, KRT6C, SERPINB5, and DSG3), selected based on a previously established 53-gene signature, we consistently observed higher expression levels in squamous cell carcinoma (SCC) compared to adenocarcinoma (ADC)." (PMID 38612418, 2024).
epidermolysis bullosa simplex (47 papers, 2005 to 2026). Epidermolysis bullosa simplex (EBS) is a group of hereditary epidermolysis bullosa (HEB) disorders characterized by skin fragility resulting in intraepidermal blisters and erosions that occur either spontaneously or after physical trauma. "Such possibilities have not been highlighted in a recent study aimed at the inactivation of a mutated KRT5 allele, causing epidermolysis bullosa simplex." (PMID 36292796, 2022). "Gene ontology annotations related to Krt5 contain structural molecule activity, and mutations in this gene are associated with epidermolysis bullosa simplex." (PMID 32411685, 2020). "For example, mutations in KRT5 or KRT14 are implicated in epidermolysis bullosa simplex, and KRT1 or KRT10 dysfunction causes bullous congenital ichthyosiform erythroderma; moreover, fragile skin structure is observed in almost all such conditions." (PMID 31581253, 2019). "Mutations in keratin 14 or keratin 5 cause a rare genetic disease called epidermolysis bullosa simplex." (PMID 25370987, 2015). "Dowling-Meara, the major subtype of epidermolysis bullosa simplex, is inherited in an autosomal dominant manner and can be caused by mutations in either the keratin-5 (K5) or the keratin-14 (K14) gene." (PMID 23894602, 2013). "In fact, sulforaphane, a chemical activator of Nrf2, restores skin integrity in an epidermolysis bullosa simplex model (created by Krt5 or Krt14 mutation) by activating Krt17 expression." (PMID 22567161, 2012). "For example, the homozygous c.1474T>C (p.S492P) mutation in the region encoding the tail domain of KRT5 is associated with epidermolysis bullosa simplex (EBS), a genetic skin disorder characterized by fragile skin that easily blisters in response to minor friction or trauma." (PMID 39930669, 2025). "Noteworthy, in an independent diagnostic screening, in family members of the paternal side (III‐3) and the sister (IV‐2) of the index patient, a KRT5 pathogenic variant c.560G>C p.(Arg187Pro) was found, establishing the diagnosis of localized epidermolysis bullosa simplex (EBSloc)." (PMID 39072839, 2024). "Generalized severe epidermolysis bullosa simplex (EBS‐gen sev) is a genetic blistering skin disease in which autosomal dominant mutations in either the keratin KRT5 or KRT14 genes lead to impaired function of the intermediate filament cytoskeleton in the basal epidermis." (PMID 30099737, 2019). "In humans, KRT5 mutations can cause the skin disease epidermolysis bullosa simplex." (PMID 25152353, 2014). "Epidermolysis bullosa simplex (EBS) is a disease arising from inherited missense mutations in KRT14 or KRT5 genes and is characterised by severe skin blistering in patients." (PMID 39408880, 2024). "For example, another dermatologic disorder, epidermolysis bullosa simplex (EBS), is associated with hotspot mutations in keratin genes KRT5 and KRT14 that result in defective cross-linking and bundle formation." (PMID 35145093, 2022). "Some of the key supporting evidence comes from studies of unconventional forms of epidermolysis bullosa simplex (EBS) and other disorders resulting from KRT5 or KRT14 mutations." (PMID 34959311, 2021). "For example, the skin blistering disease Epidermolysis Bullosa Simplex (EBS) is caused by point mutations in the Keratin 5 (K5) and 14 (K14) genes." (PMID 34323216, 2021). "Generalized severe epidermolysis bullosa simplex (EBS-gen sev) is caused by mutations within either the KRT5 or KRT14 gene, phenotypically resulting in blistering and wounding of the skin and mucous membranes after minor mechanical friction." (PMID 30382914, 2018). "Bolling M.C., Lemmink H.H., Jansen G.H.L., Jonkman M.F. Mutationsin KRT5 and KRT14 cause epidermolysis bullosa simplex in75 % of the patients." (PMID 36923479, 2023).
epidermolysis bullosa simplex (continued). "The most common type of EB is Epidermolysis Bullosa Simplex (EBS), and can be caused by autosomal recessive mutation of the desmoplakin gene in the suprabasal cells or autosomal dominant mutations in the keratin 5/14 genes in the basal cells." (PMID 36172276, 2022). "Epidermolysis bullosa simplex (EBS), associated with intraepidermal blistering, is mainly caused by mutations within genes encoding keratin 5, 14, and plectin." (PMID 36091706, 2022). "In the skin fragility disorder epidermolysis bullosa simplex (EBS), mutations in keratin 14 (K14, also known as KRT14) or keratin 5 (K5, also known as KRT5) lead to keratinocyte rupture and skin blistering." (PMID 34643242, 2021). "Epidermolysis bullosa simplex (EBS) is a rare skin condition usually caused by mutations in the keratin intermediate filament proteins keratin 5 (K5, also known as KRT5) or keratin 14 (K14, also known as KRT14), leading to skin blistering and wound development." (PMID 34643242, 2021). "Dominantly-acting missense alleles in either KRT5 or KRT14 underlie the vast majority of cases of epidermolysis bullosa simplex (EBS), a rare genetic skin disorder in which trivial trauma results in skin blistering secondary to the lysis of fragile basal keratinocytes." (PMID 32369015, 2020). "Epidermolysis bullosa simplex (EBS) is a rare genetic disorder, resulting from mutations in keratin 5 and keratin 14 (KRT14), and is characterised by skin fragility, herpetiform blistering, and the development of confluent palmoplantar keratoderma and nail dystrophy." (PMID 40700032, 2025). "AD: autosomal dominant; KRT5: gene that encodes keratin 5; KRT14: gene that encodes keratin 14; EBS: epidermolysis bullosa simplex; EBS-K, epidermolysis bullosa simplex-Koebner; EBS-WC, epidermolysis bullosa simplex Weber-Cockayne; EBS-DM, epidermolysis bullosa simplex Dowling-Meara." (PMID 38803406, 2024). "Interestingly, a translational frame shift in KRT5 is responsible for a rare form of epidermolysis bullosa simplex, whereas a frame shift in KRT1 results in a rare type of ichthyosis." (PMID 39319188, 2024). "Such mutations cause skin diseases, whereas mutations in the KRT5 gene are also considered a risk factor for the development of basal cell carcinoma, and mutations in both KRT5 and KRT14 are frequently associated with epidermolysis bullosa simplex." (PMID 39682709, 2024). "Arin M.J., Grimberg G., Schumann H., de Almeida H. Jr., Chang Y.- R.,Tadini G., Kohlhase J., Krieg T., Bruckner-Tuderman L., Has C.Identification of novel and known KRT5 and KRT14 mutations in53 patients with epidermolysis bullosa simplex: correlation betweengenotype and phenotype." (PMID 36923479, 2023). "Moreover, mutations in KRT5 and/or KRT14 are known to cause epidermolysis bullosa simplex (EBS), which is marked by skin blisters and cell fragility of basal keratinocytes." (PMID 26039063, 2015). "In the case of epidermolysis bullosa simplex (EBS), which exhibits several clinical variants, specific phenotypes can be largely correlated with the positions of missense mutations in structurally sensitive portions of either KRT5 or KRT14." (PMID 26666517, 2015). "The basic keratin CK5 may partner CK15 within skin and human KRT5 mutations cause epidermolysis bullosa simplex." (PMID 24260555, 2013).
bladder cancer (46 papers, 2015 to 2025). "Furthermore, luminal bladder cancer variants (micropapillary, plasmacytoid, nested) exhibited significantly lower levels of KRT5 and significantly higher levels of KRT20 expression than conventional UBC or basal variants (sarcomatoid, squamous)." (PMID 30380731, 2018). "In bladder cancer, KRT5/6 and KRT20 are used as combined markers in immunohistochemical analysis, which is helpful for the clinical evaluation of patient benefits from chemotherapy." (PMID 37671092, 2023). "Among the set of immunohistochemical markers, GATA3 and KRT5/6 have emerged as an effective surrogate molecular classifier of bladder cancer that correctly identified the molecular subtypes in over 80% of the cases." (PMID 32546765, 2020). "We concluded that the immunohistochemical staining with GATA3 and KRT5/6 is a simple classifier of molecular subtypes of bladder cancer which is effective in over 80% of the cases." (PMID 32546765, 2020). "This indicated that GATA3 and KRT5/6 immunohistochemical staining is the most effective classifier for prediction of luminal and basal molecular subtypes of bladder cancer." (PMID 32546765, 2020). "Interestingly, lower expressions of EGFR, KRT5, and KRT6 are associated with better survival in bladder cancer patients." (PMID 38539513, 2024). "Lineage tracing studies in the N-butyl-N-(4-hydroxybutyl)nitrosamine induced bladder cancer mouse model showed that basal cancers originate from KRT5 and sonic hedgehog-positive basal uroprogenitor cells while papillary luminal tumors are derived from the intermediate cells." (PMID 32546765, 2020). "Our laboratory demonstrated that arsenite-transformed malignant UROtsa cells exhibit characteristics of the basal muscle-invasive phenotype of bladder cancer, including high expression of basal markers such as EGFR, KRT1, KRT5, and KRT6." (PMID 38539513, 2024). "A clinical study identified KRT5, KRT6, and GATA3 expression as the most effective classifier in predicting luminal versus basal subtypes of bladder cancer with an accuracy of 89%." (PMID 38539513, 2024). "Among the top DMRs, we note many overlapping with genes known to be involved in bladder cancer, such as FGFR3, GATA3, KRT15, and KRT5." (PMID 33397444, 2021). "KRT5 or KRT20 mRNA is considered a characteristic feature for a basal or luminal lineage, respectively, in bladder cancer." (PMID 33003392, 2020). "The same study found TRIM29 gene expression to be correlated to KRT5, KRT14, KRT6A, and KRT16 expression using The Cancer Genome Atlas (TCGA) RNA sequencing data from multiple tumor types, including basal subtype bladder cancers." (PMID 32822399, 2020). "High expression of basal keratins, such as KRT5 and KRT6A, is the most characteristic feature of the basal subtype of bladder cancer." (PMID 29956121, 2018). "In five bladder cancer datasets (TCGA-MIBC, GSE13507, GSE48075, GSE32894, and GSE48276), ERBB2 was highly positively correlated with GATA3 and FOXA1 but negatively correlated with CD44 and KRT5, suggesting that ERBB2 is a luminal marker to some extent." (PMID 39840049, 2024). "Furthermore, in the TCGA bladder cancer data set, an increase correlation of TRIM29 was found with the basal genes P63, KRT5 and KRT6A suggesting a prominent role of these molecules in aggressive bladder cancers." (PMID 36293167, 2022). "In order to facilitate molecular subtyping of bladder cancer in primary care centers, we analyzed the protein expressions of signature luminal (GATA3) and basal (KRT5/6) markers by immunohistochemistry, which identified molecular subtypes in over 80% of the cases." (PMID 32546765, 2020). "Here, we have used RT-qPCR-based quantitation of predefined hallmark subtyping markers (KRT5/KRT20), with proven prognostic impact in muscle-invasive and non-muscle-invasive bladder cancer and which have been shown to have some predictive value in a finding cohort." (PMID 35887247, 2022).